LRRN4CL (LRRN4 C-terminal like)
Tractability: Antibody: UniProt predicts a signal peptide or a membrane-spanning region.
Gene: Protein-coding gene on chromosome 11 (62,686,406 to 62,689,609, reverse strand). Ensembl gene ENSG00000177363.
Subcellular location: Membrane
Subcellular location (Human Protein Atlas): Nucleoplasm; Nuclear bodies
Gene Ontology:
Cellular component: membrane
Genetic constraint (gnomAD): Missense variants: 348 observed, 303.87 expected, observed/expected ratio (o/e) 1.15, 90% interval 1.05 to 1.25. Synonymous variants: 156 observed, 140.19 expected, observed/expected ratio (o/e) 1.11, 90% interval 0.98 to 1.27.
Homologues: Orthologues: macaque LRRN4CL (96% identical), dog LRRN4CL (75% identical), mouse Lrrn4cl (68% identical), guinea pig LRRN4CL (63% identical), tropical clawed frog lrrn4cl (31% identical), zebrafish si:ch1073-303k11.2 (26% identical). Paralogues in human: LRRN4 (35% identical), ISLR2 (16% identical), ISLR (12% identical).
Diseases named in the same sentence as LRRN4CL in open-access papers:
LRRN4CL is named in the same sentence as 12 diseases in open-access papers, as found by Europe PMC text mining. Sharing a sentence is not in itself a finding about the gene and the disease. The quoted sentences say what the papers report.
breast carcinoma (3 papers, 2021 to 2025). "Among other family members, LRRN3, LRRN4, and LRRN4CL were uniformly downregulated in breast cancer tissues." (PMID 41458604, 2025). "Notably, our analysis revealed significant downregulation of LRRN1, LRRN3, and LRRN4CL in breast cancer tissues." (PMID 41458604, 2025). "As GALNTL5, MLIP, HMCN2, LRRN4CL and DUOX2 were identified as cytotoxicity-associated genes, we next investigated their effects on therapeutic response by analyzing RNA-seq data and drug sensitivity of multiple breast cancer cell lines using Pearson coefficient analysis." (PMID 35046993, 2021). "(F-J) Survival analysis was performed for GALNTL5, MLIP, HMCN2, LRRN4CL and DUOX2 using log-rank test for RNA-seq data and the corresponding survival data from the TCGA cohort of patients with breast cancer." (PMID 35046993, 2021). "The observed differential expression patterns, particularly the consistent downregulation of LRRN1, LRRN3, and LRRN4CL coupled with LRRN2 upregulation, prompted us to focus our subsequent investigations on elucidating the specific mechanisms of these proteins in breast cancer metastasis." (PMID 41458604, 2025). "To assess whether the phenotype associated with Lrrn4cl upregulation was specific to melanoma cells, we expressed the Lrrn4cl cDNA in three non-melanoma mouse cancer cell lines (MC-38 colorectal cancer cells, MB-47 bladder cancer cells and EO771 breast cancer cells) and the same effect was observed." (PMID 33758365, 2021).
thyroid cancer (2 papers, 2021 to 2022). "It is our study that collects LRRN4CL, HS3ST3A1, PCOLCE2, and CAPN8 all together for the first time and sets them as biomarkers related to TME in thyroid cancer, which might become potential candidate targets for TC immunotherapy." (PMID 36590308, 2022).
cutaneous melanoma (1 paper, 2021). A primary melanoma arising from atypical melanocytes in the skin. "High expression of LRRN4CL also correlated with poorer disease-specific survival in cutaneous melanoma patients (as assessed across two independent datasets), as well as for other cancer types." (PMID 33758365, 2021). "The TCGA database shows there is a range of LRRN4CL mRNA expression levels across 32 cancer types; expression is enriched in melanomas, with cutaneous melanoma and uveal melanoma showing the highest levels." (PMID 33758365, 2021).
glioma (1 paper, 2021). A benign or malignant brain and spinal cord tumor that arises from glial cells (astrocytes, oligodendrocytes, ependymal cells). "Analysis of the TCGA datasets also showed that high expression of LRRN4CL correlated with worse outcome in low-grade glioma, renal clear cell carcinoma and ovarian carcinoma (univariate analysis, Log-rank P = 1.17 × 10−6, 0.027 and 0.048, respectively)." (PMID 33758365, 2021).
melanoma (1 paper, 2021). A malignant, usually aggressive tumor composed of atypical, neoplastic melanocytes. "Critically, LRRN4CL expression was elevated in melanoma patient samples, with high expression levels correlating with decreased survival." (PMID 33758365, 2021). "Collectively, our findings uncover an unappreciated role for LRRN4CL in the outcome of melanoma patients and identifies a potential therapeutic target and biomarker." (PMID 33758365, 2021). "We have shown here that upregulated expression of mouse and human LRRN4CL resulted in an enhanced ability of metastatic tumour cells (both melanoma and other cell types) to colonise the lungs in mice." (PMID 33758365, 2021). "Thus, although we identified Lrrn4cl in melanoma cells, it mediates pulmonary colonisation cell lines from other tumour types." (PMID 33758365, 2021). "They find that high expression of LRRN4CL in melanoma cells increases lung metastases in mice and correlates with poorer survival in melanoma patients, suggesting it could be a promising drug target." (PMID 33758365, 2021). "As upregulated LRRN4CL expression only provided an advantage to metastatic tumour cells in the lung, with no phenotypic effect observed in vitro, we performed RNAseq of human A375 melanoma cells expressing LRRN4CL (A375_LRNmCherry cells; ‘L’) that had been colonising the lung for 21 days." (PMID 33758365, 2021). "Furthermore, Lrrn4cl expression did not affect the primary tumour growth of B16-F0 melanoma cells subcutaneously administered to wildtype mice." (PMID 33758365, 2021). "In addition, upregulated expression of LRRN4CL in melanoma cells did not result in any phenotypic difference, compared with control cells, in primary tumour growth in the skin after subcutaneous administration into the flank." (PMID 33758365, 2021). "Similarly, when mouse B16-F0 melanoma cells were tail vein dosed into immunodeficient (NOD-SCID) mice, in addition to pulmonary metastases, hepatic metastases were also noted, and expression of Lrrn4cl cDNA resulted in the cells showing significantly decreased hepatic metastatic colonisation." (PMID 33758365, 2021).
uveal melanoma (1 paper, 2021). A melanoma derived from melanocytes of the uveal tract. "The highest expression of LRRN4CL in the TCGA dataset was observed in cutaneous and uveal melanoma, both of which have a propensity to metastasise." (PMID 33758365, 2021). "Interestingly, in uveal melanoma patients, higher expression of LRRN4CL did not correlate with clinical outcome." (PMID 33758365, 2021).
tumor (4 papers, 2021 to 2025). "LRRN4CL expression patterns demonstrated significant associations with both tumor size and lymph node metastatic burden, while also exhibiting a progressive decline with advancing disease stage." (PMID 41458604, 2025). "We performed RNA sequencing for 30 pairs of TNBC tissue and matched normal tissue from our hospital, and identified five pivotal genes (GALNTL5, MLIP, HMCN2, LRRN4CL, and DUOX2), which were correlated with associated with CD8+ T cell infiltration, tumor progression and therapeutic efficacy." (PMID 35046993, 2021). "This suggests that expression of the Lrrn4cl cDNA did not enhance the ability of the tumour cells to extravasate." (PMID 33758365, 2021). "The Wilcoxon rank-sum test indicated the expression levels of 4 DEGs among normal and tumor tissue in paired or unpaired samples, which indicated HS3ST3A1 and CAPN8 expressed significantly higher in tumor tissues, while the other two genes, LRRN4CL and PCOLCE2, were not." (PMID 36590308, 2022).
cancer (3 papers, 2017 to 2021). A tumor composed of atypical neoplastic, often pleomorphic cells that invade other tissues. "Critically, high expression of LRRN4CL was significantly correlated with worse outcome in cancer patients, across all cancers represented in TCGA." (PMID 33758365, 2021). "Using the TCGA dataset, higher expression levels of LRRN4CL (top 25% quartile) significantly correlated with a poorer outcome (disease-specific survival) in cancer patients in general (all cancer types included in the analysis; Cox Log-rank P = 2.2 × 10−16, age- and sex-adjusted)." (PMID 33758365, 2021). "The modules also contained genes like LRRN4CL, NAV3 and STMN1 that have not yet been investigated in cancer research." (PMID 29371966, 2017).
LRRN4CL also shares sentences with these, for which no sentence is quoted: bladder cancer (1 paper); colorectal cancer (1); ovarian carcinoma (1); renal clear cell carcinoma (1).